EDN1 (endothelin 1)
Diseases named in the same sentence as EDN1 in open-access papers (continued):
Sharing a sentence is not in itself a finding about the gene and the disease.
colon adenoma (1 paper, 2020). An adenoma that arises from the colon. "It has been reported that prepro-EDN-1, the pre-protein of endothelin-1, was overexpressed in human colon adenomas and adenocarcinomas as compared to normal colon." (PMID 32194414, 2020).
colorectal adenocarcinoma (1 paper, 2021). The most common type of colorectal carcinoma. "In colorectal adenocarcinomas, IL6 secreted from hBMMSCs not only increased cancer cell CD133 expression via activation of the JAK2/STAT3 pathway, but also activated Akt and ERK in endothelial cells by inducing the secretion of endothelin-1 (ET-1)." (PMID 33849537, 2021).
congenital diaphragmatic hernia (1 paper, 2025). A posterolateral defect of the diaphragm that allows passage of abdominal viscera into the thorax, leading to respiratory insufficiency and persistent pulmonary hypertension with high mortality. "Elevated levels of Endothelin-1 (ET-1), a vasoactive peptide, have been associated with adverse outcomes in neonates with congenital diaphragmatic hernia (CDH)." (PMID 40119427, 2025).
Coronary artery dissection (1 paper, 2022). Acute occurrence of a dissection (tear within the tunica intima and entry of blood into the tunica media) of a coronary artery. "Case-control studies have shown that PHACTR1/EDN1 is a risk factor for several vascular diseases, such as spontaneous coronary artery dissection (SCAD)." (PMID 36046789, 2022).
Cyanosis (1 paper, 2021). Bluish discoloration of the skin and mucosa due to poor circulation or inadequate oxygenation of arterial or capillary blood. "The alignment of 5′UTR of sequences of all samples with the 5′UTR of RefSeq of edn1(NG_016196.1) revealed that 30 out of 38 sequences showed a deletion of ‘A’ at + 139 position of edn1 irrespective of cyanosis or acyanosis." (PMID 34011397, 2021).
deafness (1 paper, 2023). An inherited or acquired condition characterized by the complete loss of the ability to hear from one or both ears. "Moreover, the inclusion among the DEGs of genes involved in inner ear development and deafness (Atoh1, Edn1, Hes1, Kl, Myc, Mycn and Olig1) suggested their interaction with Dmp1 in these processes." (PMID 37106825, 2023).
encephalopathies (1 paper, 2025). "Across the spectrum of encephalopathies discussed in this review, a unifying molecular target emerges: endothelin-1 (ET-1) and its receptors." (PMID 40463938, 2025).
Fabry disease (1 paper, 2022). Fabry disease (FD) is a progressive, inherited, multisystemic lysosomal storage disease characterized by specific neurological, cutaneous, renal, cardiovascular, cochleo-vestibular and cerebrovascular manifestations. "The rSNPs proposed here could modulate the clinical phenotype of Fabry disease, so we propose that IL10, TGFB1 and EDN1 genes be considered modifier/minor genes in FD, in charge of regulating its neuro-cardiovascular variant." (PMID 36138766, 2022).
folate deficiency (1 paper, 2021). A nutritional condition produced by a deficiency of FOLIC ACID in the diet. "The WRE sequence of Ctla4 and Edn1 both exhibited decrease in intensity at the Gcm1 peak in folate deficiency." (PMID 33664222, 2021).
gout (1 paper, 2024). A condition characterized by painful swelling of the joints, which is caused by deposition of urate crystals. "The present comparative study aimed to investigate the effects of different doses of febuxostat on uric acid, inflammatory factors of serum, knee articular cavity, endothelin-1, and oxidative stress in patients with gout." (PMID 40190525, 2024).
hepatitis C (1 paper, 2021). "Patients receiving IFN-α therapy for hepatitis C also have elevated levels of endothelin-1 (ET-1), a key mediator involved in the pathogenesis of PAH, and ET-1 can be induced by interferon in vascular smooth muscle." (PMID 34442052, 2021).
hereditary haemorrhagic telangiectasia (1 paper, 2017). "Also down‐regulated are ACVRL1—mutations in which cause vessel malformations in hereditary haemorrhagic telangiectasia 46—endothelin 1 (EDN1), which encodes vasoconstrictive peptides, and CCL2, which has chemotactic activity for monocytes and basophils." (PMID 28631889, 2017).
hyperandrogenism (1 paper, 2025). Excessive secretion of androgens from the adrenal glands or gonads. "Furthermore, hyperandrogenism is highly associated with the production of ROS, the oxidation of LDL cholesterol, and the release of pro-inflammatory cytokines and vasoconstriction factors such as endothelin-1." (PMID 40564951, 2025).
Hypercalcemia (1 paper, 2020). An abnormally increased calcium concentration in the blood. "Hypercalcemia has been shown to increase the expression of renal endothelin-1, inducible nitric oxide synthase, and other pro-inflammatory cytokines in rats." (PMID 32129057, 2020).
hypoadiponectinemia (1 paper, 2018). "The greater vulnerability to contrast media, among obese individuals, might be attributed to hyperleptinemia, increased sympathetic activity, hypoadiponectinemia, and high levels of free fatty acids and endothelin-1." (PMID 30212493, 2018).
hypogonadism (1 paper, 2012). A disorder characterized by decreased function of the gonads. "Kumanov established that plasma endothelin 1 (ET1) levels are elevated in males with hypogonadism, and testosterone treatment decreases ET1." (PMID 22518131, 2012).
large artery stroke (1 paper, 2018). Stroke caused by the blockage of blood flow in one of the large arteries feeding the brain. "The aim of the present case-control study was to investigate the possible association between EDN1 rs5370 and EDNRA rs5335 polymorphisms and large artery stroke (LAS) in representatives of the Ukrainian population." (PMID 29849817, 2018). "In this study, the analysis of a possible association between EDN1 rs5370 and EDNRA rs5335 gene polymorphisms and the risk of large artery stroke (LAS) in a Ukrainian population was conducted." (PMID 29849817, 2018).
lichen planus (1 paper, 2025). A chronic, recurrent, pruritic inflammatory disorder of unknown etiology that affects the skin and mucus membranes. "Cheng et al12 investigated the tumor marker endothelin-1 in the saliva of patients with lichen planus, introducing this biomarker as a lichen planus activity assessment tool." (PMID 40265032, 2025).
lipodystrophy (1 paper, 2025). A congenital or acquired disorder characterized by abnormal loss or redistribution of the adipose tissue in the body. "Intriguingly, among the 15 overlapping downregulated genes, we noted 4 lipodystrophy genes: bscl2l, fabp7a, cidec, and edn1." (PMID 40922543, 2025).
membranous nephropathy (1 paper, 2025). "Basic endothelin 1 levels correlated negatively with albumin at many monitoring time points in the membranous nephropathy group." (PMID 41517469, 2025).
mental disorder (1 paper, 2017). A disease that has its basis in the disruption of mental process. "Several other essential genes (Gpr88 and Edn1) involved in mental disorder, learning, and memory were also suppressed in the hippocampus of Utx cKO mice." (PMID 28970783, 2017).
myopia (1 paper, 2020). "In the current study we concluded that endothelin-1 (ET-1) expression is disturbed in children and adolescents with high myopia." (PMID 32370291, 2020).
oral mucositis (1 paper, 2024). Inflammation of the mucous membranes of any of the structures in the mouth. "- GT genotype in EDN1 rs1800541 was significantly associated with an elevated risk of developing grade 3+ oral mucositis (p = 0.038)." (PMID 38473311, 2024).
osteosclerosis (1 paper, 2024). Abnormally high bone density. "In the osteosclerosis process, among various factors that stimulate osteoblast proliferation and inhibit osteoclast activity and motility, endothelin-1 (ET-1) was recognized as a major mediator." (PMID 38791037, 2024).
peripheral vascular disease (1 paper, 2025). Any disorder affecting blood flow through the veins or arteries outside of the heart. "However, in patients with peripheral vascular disease, HBOT paradoxically increased endothelin 1 (ET-1) levels which is a potent vasoconstrictor." (PMID 41462642, 2025).
phyllodes tumor (1 paper, 2005). A benign, borderline, or malignant fibroepithelial neoplasm arising from the breast and rarely the prostate gland. "Furthermore, stimulation of the stromal component by the epithelium was suggested previously by studying endothelin-1 expression in epithelium of phyllodes tumors." (PMID 16168127, 2005).
Priapism (1 paper, 2021). A painful and harmful medical condition in which the erect penis doesn't return to its flaccid state, despite the absence of both physical and psychological stimulation, within four hours. "Frequencies of EDN1 5665 G/T and NOS3−786 T/C gene polymorphisms among SCA and HbSC individuals with or without a previous history of priapism." (PMID 33539452, 2021).
pulmonary embolism (1 paper, 2010). The obstruction of the pulmonary artery or one of its branches by an embolus, sometimes associated with infarction of the lung. "Atrial natriuretic petide (ANP), brain natriuretic peptide (BNP) and endothelin-1 (ET-1) may reflect the severity of right ventricular dysfunction (RVD) in patients with pulmonary embolism (PE)." (PMID 20559433, 2010).
Retinal hemorrhage (1 paper, 2020). Bleeding located within the retina. "CD can improve retinal microneuropathy, retinal hemorrhage, exudates, and whole blood viscosity, by a mechanism related to the decrease of serum endothelin-1 and high-sensitivity C-reactive protein levels." (PMID 32963587, 2020).
secondary pulmonary hypertension (1 paper, 2012). "In COPD there is a reduction in the expression of prostacyclin synthase mRNA, and in patients with secondary pulmonary hypertension there is an excessive expression of endothelin-1 (ET-1)." (PMID 22973510, 2012).
Skin ulcer (1 paper, 2022). A discontinuity of the skin exhibiting complete loss of the epidermis and often portions of the dermis and even subcutaneous fat. "Relevant studies have reported that Panax Notoginseng Saponins (PNS) can alleviate skin ulcers in diabetic rats by reducing the expression of endothelin-1 (ET-1) and tumor necrosis factor-α (TNF-α)." (PMID 35069970, 2022).
Splenomegaly (1 paper, 2023). Abnormal increased size of the spleen. "Recovery of hepatocyte function with SOF/VEL treatment may improve the hepatic microcirculatory environment, but HVPG may not decrease in patients with splenomegaly possibly because of high amounts of endothelin-1 produced by the enlarged spleen." (PMID 36729172, 2023).
stomach tumors (1 paper, 2014). "EDN1 protein overexpression was less significant in esophagus, kidney and stomach tumors." (PMID 24416389, 2014).
thalassemia (1 paper, 2025). An inherited blood disorder characterized by a decreased synthesis of one of the polypeptide chains that form hemoglobin. "Compared with the control, the endothelin-1 levels were significantly higher in the thalassemia group." (PMID 40332500, 2025).
Thromboembolism (1 paper, 2020). The formation of a blood clot inside a blood vessel that subsequently travels through the blood stream from the site where it formed to another location in the body, generally leading to vascular occlusion at the distant site. "In the thromboembolism model, brain injury is induced by the injection of endothelin-1 or thrombin and critically depends on the potency of the peptides to form the platelet coagulation." (PMID 33244072, 2020).
Urinary incontinence (1 paper, 2023). Loss of the ability to control the urinary bladder leading to involuntary urination. "A recently published genome-wide association study in three independent discovery cohorts of 8979 European women identified a genetic variant situated near EDN1 and strongly associated with urinary incontinence." (PMID 37109658, 2023).
vascular occlusion (1 paper, 2019). "It has also been suggested that increased levels of various local mediators of vasoconstriction such as endothelin-1 and decreased aqueous levels of strong mediators of vasodilation such as nitric oxide may play a role in vascular occlusion in eyes with PEX." (PMID 31594281, 2019).
tumor (261 papers, 1992 to 2026). "Endothelin 1 increased MDA-MB-231 invasiveness, and an endothelin 1-enriched tumor phenotype has been related with a higher risk for BC recurrence." (PMID 41301028, 2025). "Although endothelin-1 (EDN1) has been implicated in tumor drug resistance, its role in oxaliplatin resistance in CRC remains poorly defined." (PMID 41425720, 2025). "Endothelin 1 (EDN1), which is implicated in several aspects of tumor progression, has been identified as a master regulator of phenotypic heterogeneity and can contribute to paracrine protection against MAPKi." (PMID 35406721, 2022). "Down-regulated in DSV-iECs, EDN1 is an angiogenic factor involved in cell proliferation, and its overexpression has been linked to tumor growth and metastasis." (PMID 32934781, 2020). "In CRC, EDN1 mRNA levels were consistently elevated in tumor tissues compared to normal tissues (p < 0.001), highlighting its CRC-specific oncogenic potential." (PMID 41425720, 2025). "During osteoblastic metastasis, tumor cells secrete endothelin-1 (ET-1) to suppress the expression of Dickkopf-1 (DKK1) in osteoblasts, thereby relieving the inhibition of the Wnt signaling pathway." (PMID 40630133, 2025). "This warrants further investigation to elucidate the interplay between EDN1 signaling and the tumor immune microenvironment." (PMID 41425720, 2025). "More recently, SOX4 has been recognized as a novel pro-angiogenic regulator, modulate the expression of endothelin-1 (ET-1) and thereby promoting tumor-induced angiogenesis." (PMID 40399256, 2025). "Endothelin-1 (ET-1) is involved in reducing the expression of ICAM-1 on tumor endothelial cells and of tumor-infiltrating leukocytes." (PMID 39325128, 2024). "In MM cells, the endothelin-1 (ET-1) receptor, by binding to autocrine ET-1, can act to prolong the survival of tumor cells." (PMID 37588219, 2024). "The overexpression of endothelin B receptor and the ligand endothelin-1 in tumors increases NO release in the endothelium, thereby impairing lymphocyte arrest and reducing tumor-infiltrating lymphocyte content in the tumor." (PMID 38726320, 2024). "The vasoconstrictive peptide endothelin 1 (ET1) is associated with ICAM-1 expression and the decreased presence of tumor-infiltrating leukocytes." (PMID 38576482, 2024). "Experimental data also show that IH activates NF-kB, HIF-1, VEGF and endothelin-1 in tumor cells and promotes tumor cell proliferation and metastasis." (PMID 37108039, 2023). "Tumor cells induce astrocytes and microglia to express endothelin-1 (ET-1), which activates survival and chemo-resistance signals in the tumor cells." (PMID 38002256, 2023). "Recently, it was reported that the interaction between keratinocytes and melanocytes through endothelin-1 (ET-1) activity is responsible for arsenic-mediated skin hyperpigmentation in hairless mice." (PMID 35362847, 2023). "The pro-tumoral properties of ADAM17, VWF, and EDN1 have been well-studied in the literature, and targeted therapy has demonstrated the effects of tumor-inhibiting." (PMID 36902193, 2023). "Epithelial cells can acquire mesenchymal phenotypes under stimulation by tumor microenvironmental factors, such as epidermal growth factor, endothelin 1, and bone morphogenetic protein, leading to metastasis and invasion of tumor cells." (PMID 37528887, 2023). "In recent years, activation of the endothelin-1 signaling axis has been found to play an important role in tumorigenesis, which is involved in tumor angiogenesis and epithelial-mesenchymal transition." (PMID 36475746, 2023). "Among the identified interactions, we suggest EDN1/EDNRB as a putative novel tumor/endothelial cell interaction, and ANG/PLXNB2 and ANG/EGFR as putative new autocrine loops in ccRCC cancer cells." (PMID 38025776, 2023). "EDN1 is considered to be the most effective vasoconstrictor in the human cardiovascular system and plays a vital role in the development of tumours." (PMID 36053810, 2022).
tumor (continued). "Mechanistically, the combination therapy inhibited tumour cell growth and promoted tumour cell death by regulating EDN1 and MAPK‐related pathways and activating the intrinsic apoptotic pathway." (PMID 36053810, 2022). "EDN1 is the most prevalent subtype in the family since it is the initial step in the creation of the peptide hormone Endothelin1 (ET-1), which promotes carcinogenesis and cancer development, particularly tumor angiogenesis." (PMID 35896520, 2022). "Local injection of endothelin-1 (ET-1, 9 μg/kg) in the site of tumor growth, 20 min after morphine injection, completely abolished morphine-induced analgesia, with mechanical thresholds returning to pre-morphine values after 5 min." (PMID 35887364, 2022). "It has been reported that interleukin-6 secreted by MSCs can increase the secretion of endothelin 1 by cancer cells, thereby enhancing tumor growth and angiogenesis, while other reports have reached the opposite conclusion." (PMID 35317758, 2022). "According to the results of cell lines, EDN1 gene knock‐down can effectively inhibit the growth of tumour cells and reduce tumour load, reflected by decreased volume and weight of tumour masses, compared to vehicle control and each agent." (PMID 36053810, 2022). "Combined treatment inhibits tumour cell growth and promotes tumour cell death by regulating EDN1 and MAPK‐related pathways, and by activating the intrinsic apoptotic pathway." (PMID 36053810, 2022). "Endothelin-1 (ET-1) released from tumor cells is a key mediator of osteoblastic metastasis; it can inhibit osteoclast bone resorption and osteoclast motility through the endothelin A (ETA) receptor." (PMID 36230816, 2022). "BTcP was induced by injection of endothelin-1 (ET-1) into the tumor, 20 min after morphine administration." (PMID 35887364, 2022). "Correlations between tumor growth, pain and EDN1 plasma levels have also been reported in animal models and patients with orofacial tumors and digestive cancer with spontaneous pain." (PMID 35295482, 2021). "Another factor involved in the stimulation of osteoblast activity is endothelin 1 (ET1), which is secreted by tumor cells." (PMID 34212564, 2021). "The vasoconstrictive peptide, Endothelin 1 (ET1), can enhance tumour angiogenesis via promoting the levels of VEGF and hypoxia inducible factor-1 (HIF-1)." (PMID 33917287, 2021). "Here we investigated the tumor-related endothelin-1 (ET-1) as an inducer of changes in MCs supporting SOC progression." (PMID 34926453, 2021). "EDN1 were implicated in cancer progression, apoptosis, EMT, stromal reaction, and tumor invasion, spread, and drug resistance." (PMID 33461176, 2021). "Osteoblasts can also be regulated by metastatic tumor cell-derived factors including endothelin 1 (ET1), dickkopf 1 (DKK1), and the Wnt signaling cascade." (PMID 34199522, 2021). "The use of an ETAR (Endothelin-1 (ET-1)/endothelin A receptor, mediating a pathway involved in OS progression) antagonist enhanced the anti-tumor effects of 14G2a mAb through the inhibition of the PI3K/Akt pathway." (PMID 34200284, 2021). "The Endothelin-1 (ET-1) axis is involved in several cancers by promoting tumor development and progression." (PMID 32850305, 2020). "Vasoconstrictive endothelin-1 (ET1) and its ETA receptor, by which ET-1 mediates vasoconstriction, are also present in cancer cells to preserve the tumor vessel contractile signal." (PMID 32865029, 2020). "In osteoblastic lesions, the arriving circulating tumor cells secrete factors such as endothelin-1 (ET-1), Wnt ligands, IGF-1, and BMPs that induce osteoblast differentiation and proliferation." (PMID 32668821, 2020). "We define a ‘core’ SOX4-transcriptional network in mammary epithelial cells that reveals an unexpected role of SOX4 in tumor-induced angiogenesis through direct regulation of Endothelin-1 (ET-1)." (PMID 30507376, 2018).